MIR8054 (microRNA 8054)
Synonyms: hsa-mir-8054
Gene: MicroRNA gene on chromosome 11 (23,419,105 to 23,419,190, reverse strand). Ensembl gene ENSG00000275868.
Homologues: Orthologues: chimpanzee MIR8054 (100% identical).